ELOA3CP (elongin A3 family member C, pseudogene)
Synonyms: formerly ELOA3C
Gene: Transcribed processed pseudogene on chromosome 18 (46,968,695 to 46,969,912, reverse strand). Ensembl gene ENSG00000275553.
Genetic constraint (gnomAD): Missense variants: 0 observed, 138.81 expected, observed/expected ratio (o/e) 0, 90% interval 0 to 0.021. Synonymous variants: 0 observed, 51.26 expected, observed/expected ratio (o/e) 0, 90% interval 0 to 0.058.